AIM2 (absent in melanoma 2)
Diseases named in the same sentence as AIM2 in open-access papers (continued):
Sharing a sentence is not in itself a finding about the gene and the disease.
autoimmune disease (26 papers, 2012 to 2025). A disorder resulting from loss of function or tissue destruction of an organ or multiple organs, arising from humoral or cellular immune responses of the individual to their own tissue constituents. "As ubiquitination is a reversible process, the regulation of deubiquitinase activity can be utilized as a new drug design strategy in the treatment of autoimmune diseases caused by excessive activation of the AIM2 inflammasome." (PMID 35693810, 2022). "Here, our study directly linked AIM2 with a prevalent autoimmune disorder." (PMID 35343082, 2022). "In this review, we systemically summarize the current research progress on the function of AIM2 and discuss its pathogenic role in autoimmune diseases and tumors, providing a better understanding of disease pathogenesis and potential diagnostic and therapeutic targets." (PMID 34014039, 2021). "While the NLP3 remains the most studied inflammasome, AIM2 has received comparatively less attention in the context of autoinflammatory and autoimmune diseases." (PMID 41369412, 2025). "Both the adaptive transfer of Aim2–/– Treg cells in T cell-mediated colitis and the specific deletion of Aim2 in Treg cells show that AIM2 is required for Treg cell stability and control of autoimmune diseases." (PMID 34697412, 2022). "AIM2 exhibits limited expression under physiological conditions but is widely expressed in many human diseases, including autoimmune diseases, and plays an essential role in the immune response." (PMID 36476420, 2022). "Similarly, DNase II deficiency promotes lysosomal DNA stress, leading to activation of cytoplasmic double-stranded DNA sensors, such as cGAS-STING and AIM2, and thereby autoinflammatory and autoimmune diseases." (PMID 40037613, 2025). "Although absent in melanoma 2 (AIM2) has been linked to inflammatory disorders, autoimmune diseases, and cancers, its role in the EMT of the retinal pigment epithelium (RPE-EMT) and retinal diseases remains unclear." (PMID 39870644, 2025). "AIM2 plays a significant role in autoimmune diseases and the activation of inflammasome." (PMID 36341437, 2022). "It has been suggested that AIM2 may play a role in neurodegenerative diseases, ischemic stroke, autoimmune diseases, cancer, etc.." (PMID 36678536, 2022). "Similarly, due to the plentiful and continuous self-DNA deposition in patients with autoimmune disease, there is a potential threat of AIM2 over-activation." (PMID 35693810, 2022). "However, our study suggested an important role of AIM2 in adaptive immune cells (TFH cells) in a classical autoimmune disease model." (PMID 35343082, 2022). "However, emerging evidence suggests a critical function for AIM2 in adaptive immunity, including in tumours and autoimmune diseases." (PMID 35343082, 2022). "In addition to innate immunity and inflammation, recent studies have revealed that AIM2 plays an essential role in cancers or autoimmune diseases in an inflammasome-independent manner by altering PI3K–AKT–mTOR signaling and immunometabolism." (PMID 34697412, 2022). "The importance of the inflammasome-dependent role of AIM2 is observed in the sensing of microbial DNA during infectious diseases and in tumorigenesis and several inflammatory and autoimmune diseases, such as atherosclerosis, neuroinflammation, psoriasis, dermatitis, arthritis, SLE, and colitis." (PMID 34697412, 2022). "AIM2 gene act as a double-edged sword in the pathogenesis of some autoimmune diseases and cancers." (PMID 36118867, 2022). "For example, synthetic oligodeoxynucleotides (ODN) A151 can inhibit immune responses by binding to AIM2, which may treat infectious and autoimmune diseases." (PMID 35145495, 2021). "Additionally, AIM2 expression was increased in autoimmune diseases, and dsDNA was recognized by AIM2 in keratinocytes to boost autoimmunity." (PMID 31427885, 2019).
autoimmune disease (continued). "Since autoimmune diseases, including AS, are frequently accompanied by uncontrolled innate immune responses to self-DNA, these findings provide a framework for comprehending the mechanisms of AIM2 activation and its interaction with inflammation, mitophagy, and oxidative stress." (PMID 41369412, 2025). "In addition, it would be important to investigate whether the T cell-intrinsic function of AIM2 affects autoimmune diseases and other immune-related diseases, including cancer and the anti-tumor immune response." (PMID 35216346, 2022). "Overall, our study provides a new mechanism by which the innate immune receptor, AIM2, protects against STZ induced-T1D by regulating intestinal homeostasis and inhibiting gut microbiota translocation, events that are strongly associated with the development of autoimmune disorders." (PMID 32295112, 2020). "Taken together, lysosomal DNA stress can promote autoinflammatory and autoimmune diseases via TLR9, cGAS-STING and AIM2 activation." (PMID 40037613, 2025). "AIM2 enhanced Treg cell stability by reducing AKT-mTOR signaling and modifying immune metabolism, thereby alleviating autoimmune diseases." (PMID 39600708, 2024). "Given the central role of AIM2 inflammasome in inflammatory pathologies, M2exo@HMPB—a biomimetic mineralization inhibitor—holds therapeutic potential beyond VaD, including neurodegenerative and autoimmune diseases." (PMID 40521199, 2025). "Recent studies had revealed that AIM2 enhanced the stability of Treg cells by attenuating AKT phosphorylation, mTOR and MYC signaling, and glycolysis, while promoting lipid oxidative phosphorylation, thereby ameliorating autoimmune diseases." (PMID 39600708, 2024). "Absent in melanoma 2 (AIM2), an essential component of the inflammasome, acts as a sensor of double‐stranded DNA and plays an important role in antiviral and antibacterial defenses, as well as in autoimmune diseases involving its own DNA." (PMID 37177836, 2023). "Notably, activation of DNA sensors DNA-PK and AIM2 can also suppress the activation of cGAS, which may be a negative feedback regulation mechanism formed by the immune system to avoid the excessive activation of its innate immune signals and prevent the occurrence of autoimmune diseases." (PMID 36189363, 2022). "Despite these results, which demonstrate that the AIM2 receptor is an important immunological target in autoimmune diseases, there is no direct or indirect evidence of AIM2 involvement in T1D." (PMID 32295112, 2020). "However, given that NLRP3, AIM2, and P2X7-NLRP3 are the most thoroughly studied in terms of pyroptosis in the context of autoimmune disease, we mainly introduce the biological characteristics of these inflammasomes and discuss their activation and modification patterns." (PMID 35693810, 2022). "Thus suggesting that certain aspects of inflammatory disorders and autoimmune diseases could be attributed to other nucleic acid sensing receptors such as RIG-1, Mda5 and AIM2." (PMID 23936008, 2013).
colitis (23 papers, 2016 to 2025). Inflammation of the colon. "Studies on Aim2-/- mice have shown a higher incidence of colitis-associated CRC compared to Asc-/-mice with defective inflammasomes, suggesting that AIM2's impact on CRC is not dependent on inflammasome activation." (PMID 39744568, 2025). "AIM2-deficient mice are highly susceptible to DSS-induced colitis and have a high colonic burden of E. coli, a commensal bacterium." (PMID 37191444, 2023). "The colonization of germ-free mice with microbiota from the AIM2-deficient mice caused higher susceptibility to colitis compared to the colonization of germ-free mice with microbiota from the wild-type mice." (PMID 37191444, 2023). "The dysbiotic gut microbiota in mice deficient in AIM2 is accompanied by the expansion of colitogenic pathobionts, as the transmission of microbiota in Aim2−/− mice renders the co‐housed WT mice susceptible to colitis." (PMID 34705319, 2021). "The susceptibility of AIM2−/− mice to autoimmune/inflammatory disease was previously reported in a DSS-induced colitis model." (PMID 32295112, 2020). "In addition, studies have found that AIM2 protects mice from DSS induced colitis, while Aim2 deficient mice are more susceptible to colitis." (PMID 38455052, 2024). "AIM2-deficient mice showed reduced production of IL-1β and IL-18, but infusion of IL-18 alleviated the higher colonic burden of E. coli and susceptibility to colitis." (PMID 37191444, 2023). "A previous study indicated that in colitis-associated CRC,there was a notable increase in both the quantity and size of tumors in the mesocolon and distal colons of Aim2-/- mice compared to WT mice." (PMID 39744568, 2025). "To further validate the mechanism by which IMP alleviates GSDMD-mediated macrophage pyroptosis via AIM2 in mice, we performed double immunofluorescence staining for F4/80 and AIM2 on colon tissues from IMP-treated TNBS-induced colitis (CD) mice." (PMID 40915382, 2025). "AIM2 promoted Th17 cell differentiation and mediated the development of colitis by regulating RORγt transcriptional activity." (PMID 39600708, 2024). "Previous studies have highlighted AIM2 activation in the pathophysiology of several autoimmune and inflammatory diseases, such as systemic lupus erythematous, colitis, and type 2 diabetes." (PMID 39352743, 2024). "Concurrently, IRF4 modulates AIM2 expression during Th17 cell differentiation, thereby playing a crucial role in the pathogenesis of colitis." (PMID 39600708, 2024). "In fact, authors suggest that the role of AIM2 in colitis is to control the anti‐microbial peptide production (such as α‐ and β‐defensins) in IEC, and to regulate tissue repair, activating an IL‐18‐dependent pathway." (PMID 30098204, 2018). "Hence, the suppression of IL-22BP related to AIM2 deletion caused the loss of the STAT3-dependent antimicrobial peptides (AMPs) Reg3β and Reg3γ, which promoted dysbiosis-linked colitis." (PMID 39684769, 2024). "Researches demonstrated that the expression of Aim2 is markedly reduced in tumor-associated tissues of mice, and mice lacking Aim2 are hypersusceptible to both colitis-associated and spontaneous colorectal tumorigenesis." (PMID 36741232, 2023). "Therefore, AIM2 is a DNA sensor that responds to intestine damage and participates in colitis, pathogen invasion, and bowel cancer." (PMID 37191444, 2023). "Intriguingly, limited reports found that AIM2 activation could protect intestinal epithelium by maintaining homeostasis, and AIM2 knockout exacerbates experimental colitis induced by DSS41,42." (PMID 37740137, 2023). "We hypothesize that AIM2 also enhances inflammation by exacerbating intestinal injury in human colitis." (PMID 37740137, 2023). "We propose that AIM2 may play the pro-inflammatory role in human colitis while genetic ablation in an experimental colitis model could result in mice being unable to resist microbial invasion, leading to more severe tissue damage." (PMID 37740137, 2023).
colitis (continued). "To determine whether AIM2 could also affect the differentiation or inflammatory potential of naïve T cells in vivo, we employed a well-known adoptive transfer model of colitis." (PMID 35216346, 2022). "By contrast, formation of other colitis-relevant inflammasomes such as AIM2, NLRP6, and NLRC4 by DSS was comparable in colons between control and UVRAGFS-expressing mice, highlighting a critical role of the NLRP3 inflammasome in UVRAGFS-associated colitis." (PMID 31831743, 2019). "AIM2 knockout mice are more severely affected by colitis and present a higher bacterial burden; however, how AIM2 is activated or how DNA is delivered in the epithelial cells during colitis is unknown." (PMID 30098204, 2018). "LPS, nigericin or ATP stimulated J774A.1 cells and LPS, nigericin, NLRC4 and AIM2 stimulated BMDMs cells in vitro and DSS-induced C57BL/6 mice model of colitis in vivo." (PMID 37367886, 2023). "Moreover, the STZ-injected AIM2−/− mice exhibited an increased fecal E. coli expression, which corroborates the data from the DSS-induced colitis model, with mice lacking AIM2 exhibiting more E. coli translocation to the colon and an increased susceptibility to colitis development." (PMID 32295112, 2020). "The absence of AIM2 affected caspase-1 activation and the production of IL-1β and IL-18, whilst also making mice highly susceptible to DSS-induced colitis associated with microbial dysbiosis." (PMID 39684769, 2024). "Regulation of the NLRP3 inflammasome using herbal compounds can affect the development of colitis via multiple mechanisms, whereas previous studies have shown that other inflammasome forming NLRs such as NLRP1, NLRP6, NLRC4 and AIM2 are also involved in the pathogenesis of colonic inflammation." (PMID 36090968, 2022). "The lack of AIM2 results in gut dysbiosis, thereby increasing the susceptibility to DSS‐induced colitis." (PMID 34705319, 2021). "Although deficiency in other inflammasome components, including ASC, caspase-1, and IL-18, also led to dysbiosis and exacerbated colitis, deficiency in NLRC4, NLRP10, NLRP12, and AIM2 had no impact on the susceptibility of WT mice to colitis upon cohousing." (PMID 26925061, 2016). "Lack of AIM2 results in imbalanced gut ecology and increased susceptibility to DSS-induced colitis." (PMID 38455052, 2024). "Notably, the colitis phenotype of AIM2 deficient mice is not entirely E. coli dependent, as despite high E. coli burden, AIM2 deficient mice still exhibit reduced colitis symptoms, indicating other unidentified bacteria migrating from wild-type to AIM2 deficient mice may protect the mouse colon." (PMID 38455052, 2024). "Mice lacking AIM2, which were treated with ABX before being treated with DSS, exhibited less body weight loss, a decreased diarrhea score, less colon inflammation and, consequently, did not develop colitis." (PMID 32295112, 2020). "Moreover, in the DSS-induced colitis model, mice lacking AIM2 also show a reduced antimicrobial peptide expression, associated with gut microbiota dysbiosis, bacterial translocation and increased colitis susceptibility." (PMID 32295112, 2020). "We also show that lack of AIM2 also supports the stability FOXP3+ cells in vitro and their differentiation in vivo during a naïve T cell transfer model of colitis." (PMID 35216346, 2022).
COVID-19 (22 papers, 2021 to 2025). A disease caused by infection with severe acute respiratory syndrome coronavirus 2. "Another inflammasome, AIM2, involved in production of IL-1 has also been found to be implicated in COVID-19." (PMID 35431536, 2022). "Specifically, AIM2 has been found to be overexpressed in nasopharyngeal epithelial cells and peripheral blood mononuclear cells (PMBCs) from COVID-19 patients and to correlate with disease severity." (PMID 40788382, 2025). "The fold-change expression of MDA5 (P = 0.0006), ZBP1 (P <0.0001), and AIM2 (P = 0.0004) in the nasopharyngeal epithelial cells from all COVID-19 patients was significantly higher than the healthy control group." (PMID 38714196, 2024). "In a previous study, it was shown that AIM2 transcript was significantly upregulated in lung tissue samples of COVID-19 patients compared with healthy control subjects." (PMID 38714196, 2024). "Several IFN-related genes, such as SPATS2L, OAS2, ISG15, ZBP1, and IFI44L, exhibited similar patterns of upregulation across both dengue and COVID-19 datasets, while others, such as AIM2 and RTP4, showed distinct regulation." (PMID 38444851, 2024). "In a pattern similar to that of ZBP1 mRNA expression, the expression of AIM2 in nasopharyngeal epithelial cells was significantly higher than PBMC samples of COVID-19 patients with mild disease (P = 0.03)." (PMID 38714196, 2024). "Analysis with confocal microscopy confirmed ASC specks co-localized with AIM2 in COVID-19 monocytes." (PMID 36703213, 2023). "AIM2 expression has been reported to be elevated in severe COVID-19 patients." (PMID 40788382, 2025). "This study examined expression of key viral nucleic acid sensor genes MDA5, ZBP1, and AIM2 in nasopharyngeal epithelial cells and peripheral blood mononuclear cells (PBMCs) obtained from 153 COVID-19 patients across a spectrum of disease severity (mild, severe, and critical) and 42 healthy controls." (PMID 38714196, 2024). "Our research shows that male COVID-19 patients exhibit increased expression of AIM2 and ZBP1 genes, which could be a crucial factor in the sex-specific immune reactions in this disease." (PMID 38714196, 2024). "There was a significant elevation in AIM2 molecules in patients of COVID-19." (PMID 38714196, 2024). "This study aimed to address two specific knowledge gaps: 1) How do expression patterns of critical viral sensor genes (MDA5, ZBP1, and AIM2) differ between immune cell populations (peripheral blood mononuclear cells [PBMCs]) and airway epithelial tissue in COVID-19 patients?" (PMID 38714196, 2024). "It was speculated that the ability of SARS-CoV-2 to induce AIM2 inflammasome response is due to the presence of cell free DNA (cfDNA) in several tissues of COVID-19 patient including lungs." (PMID 37360532, 2023). "Besides NLRP3, other types of inflammasomes that were initially known to interact with dsRNA or bacteria such as AIM-2, caspase-4 and -8 were found to play a role in the inflammation responses during COVID-19." (PMID 37360532, 2023). "It is shown that the AIM2 inflammasome is activated in monocytes from patient with COVID-19." (PMID 36703213, 2023). "In another study, researchers showed that AIM2 might play a vital role in the immunopathogenesis of COVID-19 patients including primary pneumonia to respiratory failure and systemic disease." (PMID 36320810, 2022). "Accordingly, these results indicated that AIM2 signaling might contribute to an unbalanced immune response in COVID-19 patients characterized by enhanced inflammatory responses, reduced antiviral signaling, potentially leading to tissue damage or disease severity." (PMID 36320810, 2022). "In addition, increased expression of MDA5 in females may be due to stronger and more appropriate immune responses against SARS-CoV-2, and elevated expression of AIM2 and ZBP1 genes might be associated with the more severe manifestation of COVID-19 in male patients." (PMID 38714196, 2024).